PGAM2 (phosphoglycerate mutase 2)
Description:
Catalyzes the interconversion of 3- and 2-phosphoglycerate with 2,3-bisphosphoglycerate as the primer of the reaction. Can also catalyze the interconversion of (2R)-2,3-bisphosphoglycerate and (2R)- 3-phospho-glyceroyl phosphate, but with a reduced activity.
Synonyms: PGAM-M; PGAMM; GSD10
Tractability: PROTAC: ubiquitination databases record sites on it.
Gene: Protein-coding gene on chromosome 7 (44,062,727 to 44,065,605, reverse strand). Ensembl gene ENSG00000164708.
Subcellular location (Human Protein Atlas): Nucleoplasm; Cytosol; Nucleoli
Pathways (Reactome):
Metabolism: Gluconeogenesis; Glycolysis
Gene Ontology:
Molecular function: identical protein binding; phosphoglycerate mutase activity; protein binding; bisphosphoglycerate mutase activity; catalytic activity; intramolecular phosphotransferase activity
Biological process: glycolytic process; striated muscle contraction; canonical glycolysis; gluconeogenesis; response to mercury ion; spermatogenesis
Cellular component: extracellular exosome; nucleoplasm; nucleus; cytosol; ooplasm
Genetic constraint (gnomAD): Loss-of-function variants: 23 observed, 22.93 expected, observed/expected ratio (o/e) 1, 90% interval 0.72 to 1.42. The upper end of that interval is the gene's LOEUF score, 1.42, which puts it in group 5 of 6, group 1 being the genes least tolerant of losing a copy. Missense variants: 349 observed, 361.69 expected, observed/expected ratio (o/e) 0.96, 90% interval 0.88 to 1.05. Synonymous variants: 133 observed, 140.06 expected, observed/expected ratio (o/e) 0.95, 90% interval 0.82 to 1.1.
Homologues: Orthologues: chimpanzee PGAM2 (100% identical), macaque PGAM2 (99% identical), rabbit PGAM2 (96% identical), pig PGAM2 (96% identical), guinea pig PGAM2 (94% identical), rat Pgam2 (94% identical), mouse Pgam2 (92% identical), zebrafish pgam2 (87% identical), tropical clawed frog pgam2 (85% identical), Drosophila melanogaster Pglym87 (68% identical), Drosophila melanogaster Pglym78 (68% identical), dog PGAM2 (61% identical). Paralogues in human: PGAM1 (81% identical), PGAM4 (78% identical), BPGM (52% identical).
Diseases named in the same sentence as PGAM2 in open-access papers:
PGAM2 is named in the same sentence as 40 diseases in open-access papers, as found by Europe PMC text mining. Sharing a sentence is not in itself a finding about the gene and the disease. The quoted sentences say what the papers report.
glycogen storage disease X (6 papers, 2016 to 2025). "A DNA sequencing-based neuromuscular genetic panel identified a heterozygous pathogenic variant and two variants of uncertain significance in his PGAM2 genes, leading to a diagnosis of glycogen storage disease X." (PMID 39463617, 2024). "Diseases associated with PGAM2 include glycogen storage disease X and phosphoglycerate mutase deficiency." (PMID 31121943, 2019). "A deficiency in PGAM2 in muscles leads to a metabolic myopathy known as glycogen storage disease X." (PMID 40707487, 2025). "Biallelic LoF variants in the PGAM2 gene may be responsible for muscle phosphoglycerate mutase deficiency, known as well as glycogen storage disease X, or for rhabdomyolysis." (PMID 33727708, 2021).
heart failure (6 papers, 2013 to 2025). Inability of the heart to pump blood at an adequate rate to meet tissue metabolic requirements. "Thus, Pgam2 mice developed heart failure associated with enhanced cardiac hypertrophy and fibrosis." (PMID 23951293, 2013). "In our previous study, we showed that PGAM2 is elevated in the serum of patients with heart failure and correlates with the disease severity and patient's prognosis." (PMID 39897023, 2025). "Collectively, our study identified PGAM2 as a novel regulator of myocardial hypertrophy, suggesting its potential as a therapeutic target for the treatment of heart failure." (PMID 39897023, 2025). "In our previous study, we showed that PGAM2 levels are elevated in the serum of heart failure (HF) patients and positively correlated with the severity of HF5." (PMID 39897023, 2025). "Our previous study showed PGAM2 levels are elevated in the serum of heart failure patients and correlate with the disease severity." (PMID 39897023, 2025). "Taken together, we first demonstrated that downregulation of PGAM2 alleviates cardiac hypertrophy induced by Ang II, which provides a novel target for the treatment of myocardial hypertrophy and heart failure." (PMID 39897023, 2025). "Pgam2 protein expression increased approximately 5-fold in a canine model of tachycardia-induced heart failure." (PMID 23951293, 2013). "More recently, a study revealed that FTO could alleviate cardiac dysfunction in mice with pressure overload-induced heart failure by regulating glucose uptake and glycolysis through facilitating the expression of glycolysis-related genes such as phosphoglycerate mutase 2 (PGAM2)." (PMID 35628623, 2022). "We could show that genes important for ATP biosynthesis and electron transport (e.g., PGAM2, NDUFA1, and TMEM126A) are consistently downregulated in heart failure." (PMID 38573186, 2024). "However, Pgam2 mice with TAC showed decreased systolic function and increased lung weight, which indicated the development of heart failure." (PMID 23951293, 2013).
glycogen storage disease (5 papers, 2013 to 2025). "Another enzyme is PGAM2, related to glycolytic pathways, with mutations causing glycogen storage disease." (PMID 26109061, 2015). "PGAM2 is an enzyme involved in the glycolytic pathway, mutations in which are associated with glycogen storage disease [MIM: 261670], a defect that causes muscle cramping, myoglobinuria and intolerance for strenuous exercise." (PMID 24039605, 2013). "Gain-of-function mutations or upregulation of PYGM (Muscle Glycogen Phosphorylase) and PGAM2 (Phosphoglycerate Mutase 2) give rise to glycogen storage diseases, resulting in severe muscle weakness, exercise intolerance, and an increased risk of muscle injury." (PMID 40149400, 2025).
breast carcinoma (3 papers, 2016 to 2023). "For instance, the performance of the TransMIL algorithm is poor when predicting the expression levels of SPRR3, a marker for terminal squamous cell differentiation linked with tumor progression in early stage breast cancers, and PGAM2, a gene involved in oxidative stress responses." (PMID 37860768, 2023).
cardiac hypertrophy (3 papers, 2013 to 2025). "We showed that PGAM2 deficiency ameliorated Ang II induced cardiac hypertrophy as indicated by decreased LV mass, left ventricular walls thickness, as well as reduced expression of ANP, BNP and β-MHC." (PMID 39897023, 2025). "In the present study, we clarified for the first time that PGAM2 expression was elevated significantly upon the stimulation of Ang II, while PGAM2 deficiency could reverse the cardiac hypertrophy induced by Ang II both in vitro and in vivo." (PMID 39897023, 2025). "PGAM2 deficiency improved the myocardial hypertrophy caused by Ang II." (PMID 39897023, 2025). "However, whether knockdown PGAM2 level could decrease susceptibility to stress and its involvement in cardiac hypertrophy remains unknown." (PMID 39897023, 2025). "However, whether PGAM2 plays a role in the regulation of cardiac hypertrophy and the underlying molecular mechanisms remain unclear." (PMID 39897023, 2025). "The present study aims to elucidate the role and mechanisms of phosphoglycerate mutase 2 (PGAM2) in the pathogenesis of cardiac hypertrophy." (PMID 39897023, 2025). "In vivo, we further confirmed that PGAM2 knockdown alleviated cardiac hypertrophy through downregulation of HSP90 and mTOR/IKKα signaling pathway." (PMID 39897023, 2025). "In the present study, we demonstrated for the first time that PGAM2 functions as a crucial regulator of cardiac hypertrophy." (PMID 39897023, 2025). "We showed that the deficiency of PGAM2 accelerated the degradation of HSP90 and alleviated Ang II-induced cardiac hypertrophy." (PMID 39897023, 2025). "In our present study, we clarify that PGAM2 is upregulated in both NRVMs and rat models of Ang II-induced cardiac hypertrophy." (PMID 39897023, 2025). "In summary, our study demonstrated for the first time that PGAM2 played important role in regulating pathological cardiac hypertrophy through interacting and modulating HSP90 stability and its downstream mTOR and IKKα / NFκB signaling." (PMID 39897023, 2025). "HSP90, which is an important molecular chaperone and critical in the regulation of cardiac hypertrophy, was identified as one of the interacting proteins of PGAM2." (PMID 39897023, 2025). "Our findings from both in vitro and in vivo experiments showed that the expression of PGAM2 was significantly elevated in models of cardiac hypertrophy induced by Ang II, while PGAM2 knockdown could alleviate Ang II-induced cardiac hypertrophy." (PMID 39897023, 2025). "This changing profile of PGAM2 indicates that it may play a role in Ang II induced cardiac hypertrophy." (PMID 39897023, 2025). "Therefore, to further elucidate the molecular mechanism by which PGAM2 participates in the regulation of cardiac hypertrophy through HSP90, we examined the signaling pathways related to mTOR and IKKα." (PMID 39897023, 2025). "Besides the in vitro study, meanwhile, we verified the role of PGAM2 in the regulation of cardiac hypertrophy in vivo." (PMID 39897023, 2025). "To further determine whether PGAM2 is involved in the regulation of Ang II induced cardiac hypertrophy, we conducted experiments to test the cardiac hypertrophy indicators ANP, BNP and β-MHC expression in NRVMs with PGAM2 knockdown or overexpression." (PMID 39897023, 2025). "However, the relationship between PGAM2 and IKKα/NFκB, as well as the underlying molecular mechanism involved in the regulation of cardiac hypertrophy, has not been reported." (PMID 39897023, 2025). "Therefore, deficiency of PGAM2 results in the downregulation of the HSP90 and its downstream mTOR and client protein IKKα signaling pathway, both of which play crucial roles in the progression of cardiac hypertrophy." (PMID 39897023, 2025). "We demonstrated that PGAM2 is involved in the regulation of cardiomyocyte hypertrophy through HSP90, which is a key factor in the progression of cardiac hypertrophy and has numerous client proteins." (PMID 39897023, 2025).
cardiac hypertrophy (continued). "Ang II exposure led to elevated mRNA and protein levels of cardiac hypertrophy indicators ANP, BNP and β-MHC, while PGAM2 silence attenuated these effects." (PMID 39897023, 2025). "However, whether PGAM2 is involved in the regulation of cardiac hypertrophy is unknown." (PMID 39897023, 2025). "In our present study, we demonstrate that PGAM2 is involved in the regulation of mTOR and IKKα/ NFκB signaling through modulation of HSP90 stability, ultimately contributing to Ang II-induced cardiac hypertrophy." (PMID 39897023, 2025). "Fatty acid oxidation (Acadm, Etfdh, Acadl, Acadvl, Eci1, Hadh, Phyh, Acaa2, Hadha, Hadhb, Cd36), glucose metabolism (Dld, Pdha1, Pgam1, Pgam2, Acss1, Ldhb, Fh1, Slc2a4, Aldh6a1), TCA cycle (Aco2, Dld, Fh1, Ogdh, Sucla2, Sdha, Idh3b, Idh2) were up-regulated by hispidulin in cardiac hypertrophy." (PMID 33324687, 2020).
myocardial ischemia (3 papers, 2012 to 2022). A disorder of cardiac function caused by insufficient blood flow to the muscle tissue of the heart. "Proteins, such as LDHB, PGAM2, GOT1, PKM2 or AK1, whose expressions are decreased in hCOX-2 Tg animals, have been identified as potential biomarkers during myocardial ischemia." (PMID 36362254, 2022). "Among them, four glycolytic enzymes, L-LDH, GAPDH, GPI, PGAM2, and two targets of MMP, gelsolin and isoform 8 of titin, are significantly released into the effluent during myocardial ischemia." (PMID 22443514, 2012). "It was reported that type-M of PGAM2 was specifically expressed in muscles and could be a potential biomarker for early myocardial ischemia, while there is still no related research of Pgam2 in kidney injury." (PMID 36465563, 2022).
endometrial cancer (2 papers, 2017 to 2024). Primary or metastatic malignant neoplasm involving the endometrium (mucous membrane that lines the endometrial cavity). "Western blotting verification data demonstrated that costars family protein ABRACL, phosphoglycerate mutase 2 were present only in endometrial cancer uterine aspirate while fibrinogen beta chain, annexin A3 were also present in healthy aspirates." (PMID 29312627, 2017). "ABRACL and PGAM2 were indicated as the most promising biomarkers for endometrial cancer diagnosis." (PMID 39194522, 2024). "ABRACL, PGAM2, FGB, and ANXA3 were identified as endometrial cancer-specific proteins, and their expression was validated through WB." (PMID 39194522, 2024). "From the discovery phase, four proteins (costars family protein ABRACL, phosphoglycerate mutase 2, fibrinogen beta chain, annexin A3) were found to be present in the uterine aspirate of endometrial cancers and not in healthy aspirates." (PMID 29312627, 2017). "In this study, western blot (WB) analysis from ten endometrial cancer vs six normal endometrium was used to validate the abundance of the four proteins which discriminate unambiguously between cases and controls (ABRACL, PGAM2, FGB, ANXA3)." (PMID 29312627, 2017).
Myocardial fibrosis (2 papers, 2013 to 2025). "Meanwhile, Sirius red staining results showed aggravated myocardial fibrosis after Ang II stimulation, which was improved by PGAM2 silence." (PMID 39897023, 2025).
Obesity (2 papers, 2021 to 2022). Accumulation of substantial excess body fat. "Since the glycolytic beige fat has been emphasized in promoting energy metabolism and thermogenesis, regulating glycolysis in AT via targeting PGAM2 could be a potential approach for obesity treatment." (PMID 35894174, 2022). "Pgam2-Tg mice also displayed their similar features with respect to body weight and IPGTT both under physiological and high fat-induced obesity conditions, compared with those of wild-type mice." (PMID 33914812, 2021). "However, the function of other DEGs like GPR183 and PGAM2 in the progress of obesity is lacking and remains to be explored." (PMID 35894174, 2022).
gastric cancer (1 paper, 2021). A primary or metastatic malignant neoplasm involving the stomach. "Regarding the gastric cancer cell line BGC-823, the Pkm, Pfkl, Ldha, Eno1, and Pgam2 mRNA expression levels were significantly elevated in the NE treatment group." (PMID 33855088, 2021).
glioma (1 paper, 2021). A benign or malignant brain and spinal cord tumor that arises from glial cells (astrocytes, oligodendrocytes, ependymal cells). "Moreover, IDH1 wild-type gliomas displayed a significantly increased expression of glycolytic enzyme genes (LDHA, HK2, PGAM2, PGK1, PKM, TIGAR) compared to IDH1-mutant gliomas as shown in heatmaps." (PMID 33493139, 2021).
leiomyosarcoma (1 paper, 2025). An uncommon, aggressive malignant smooth muscle neoplasm, usually occurring in post-menopausal women. "Consistent with the pathological diagnosis of leiomyosarcoma, 53KOLS cells expressed Pgam2 considerably higher than Pgam1." (PMID 40707487, 2025).
oral cancer (1 paper, 2019). "Glycolytic enzymes Aldoa, Hk2, Tpi1, Pgam2, Pfkl, and Pkm2 as well as the PKA-AMPK pathway genes Prkaa2, Pde4a, Pde10a, Ywhag, and Crebbp were downregulated by BRBs during oral cancer chemoprevention." (PMID 31336728, 2019).
psoriasis (1 paper, 2021). An autoimmune condition characterized by red, well-delineated plaques with silvery scales that are usually on the extensor surfaces and scalp. "Based on the sequencing results, the genes of CBS, Sardh, GNMT, Pgam2, and Sdsl in the Gly-Ser-Thr axis were selected for the determination of protein concentrations on day 12 to explore the involvement of this metabolic pathway in the TDG treatment of psoriasis." (PMID 33995034, 2021).
Sepsis (1 paper, 2026). Sepsis is defined as life-threatening organ dysfunction caused by a dysregulated host response to infection. "This study aims to investigate the role of PGAM2 in sepsis-induced diaphragmatic atrophy and its underlying mechanisms." (PMID 42193400, 2026). "PGAM2 may therefore serve as a potential therapeutic target for sepsis-associated diaphragmatic dysfunction." (PMID 42193400, 2026). "Phosphoglycerate mutase 2 (PGAM2), a key enzyme in glycolysis, plays a significant role in muscle energy metabolism but has not been previously linked to sepsis-induced diaphragmatic dysfunction." (PMID 42193400, 2026).
serous papillary adenocarcinoma (1 paper, 2017). "The western blot data verified the presence of PGAM2 in all EC patients, behaving as a marker for G1, G2, G3, G2-G3 and serous papillary adenocarcinoma EC phase." (PMID 29312627, 2017).
skin tumours (1 paper, 2019). "The rabbit skin tumours induced via blood infection displayed decreased expression of SLN, TAC1, MYH8, PGAM2, and APOBEC2 and increased expression of SDRC7, KRT16, S100A9, IL36G, and FABP9, as seen in tumours induced by local infections." (PMID 31340720, 2019).
soft tissue sarcoma (1 paper, 2025). A malignant neoplasm arising from muscle tissue, adipose tissue, blood vessels, fibrous tissue, or other supportive tissues excluding the bones. "TCGA dataset in soft tissue sarcoma showed that PGAM2 expression positively correlates with MEF2A and MEF2D expression." (PMID 40707487, 2025).
squamous cell carcinoma (1 paper, 2015). A carcinoma arising from squamous epithelial cells. "We document that PGAM interacts with several 40S and 60S ribosomal proteins and that silencing of PGAM2 expression results in disturbance of nucleolar structure, inhibition of RNA synthesis and decrease of the mitotic index of squamous cell carcinoma cells." (PMID 26033454, 2015).
Stroke (1 paper, 2023). Sudden impairment of blood flow to a part of the brain due to occlusion or rupture of an artery to the brain. "Based on the role of metabolism in stroke, we extracted seven genes related to the “porphyrin metabolism” and “glycine, serine and threonine metabolism” pathways, including ALAS2, FECH, COX10, GCAT, HMBS, PGAM2, and AOC2." (PMID 36968495, 2023).